NLRP3 (NLR family pyrin domain containing 3)
Diseases named in the same sentence as NLRP3 in open-access papers (continued):
Sharing a sentence is not in itself a finding about the gene and the disease.
type 2 diabetes (continued). "Many multifactorial diseases, such as gouty arthritis, atherosclerosis, and type 2 diabetes, are exacerbated by NLRP3-mediated inflammation." (PMID 35992142, 2022). "The NLRP3 inflammasome has been regarded as a critical signal for the pathogenesis of metabolic and degenerative diseases, such as type 2 diabetes, arteriosclerosis, and Alzheimer’s diseases." (PMID 36577816, 2022). "The NLRP3 inflammasome, in particular, has been widely investigated and is involved in a number of diseases, including type 2 diabetes and diabetic wounds." (PMID 35992142, 2022). "Glyburide, an ATP-sensitive K+ channel inhibitor used in the treatment of type 2 diabetes, is capable of inhibiting the NLRP3 inflammasome and decreasing IL-1β production." (PMID 35456141, 2022). "The expressions of TXNIP and NLRP3 are both increased in type 2 diabetic patients’ circulating immune cells." (PMID 36142531, 2022). "Studies have revealed a close relationship between the NLRP3 inflammasome and the development of inflammatory diseases such as type 2 diabetes mellitus (T2DM), Alzheimer's disease, atherosclerosis, and gout." (PMID 35495917, 2022). "Glyburide, a type 2 diabetes drug, was the first repositioned drug identified to inhibit the NLRP3 inflammasome by blocking ATP-sensitive K+ channels and reducing LPS-induced lethality in mice." (PMID 35669789, 2022). "According to one recent study, M1 macrophage infiltration and NLRP3 inflammasomes both increased in cardiac ventricular muscles in mice models of type 2 diabetes after stroke." (PMID 36142531, 2022). "TXNIP is a critical signalling protein that mediates inflammation and pancreatic β cell death, while NLRP3 inflammasome is responsible for the trigger of islet inflammation in type 2 diabetes." (PMID 36079752, 2022). "The concentrations of NLRP3 in serum and saliva of patients with periodontitis and periodontitis + type II diabetes mellitus were higher than those of healthy controls and type II diabetes mellitus patients." (PMID 34777632, 2021). "NLRP3 inflammasome expression and activation were found to be increased in monocyte-derived macrophages from patients with newly diagnosed type 2 diabetes." (PMID 34776995, 2021). "As such, CY-09 specifically inhibits the activation of NLRP3 inflammasome and has remarkable therapeutic effects in mouse models of some NLRP3-driven diseases like type 2 diabetes." (PMID 34630429, 2021). "IL-1β is a prominent pro-inflammatory mediator that is also involved in the pathogenesis of type 2 diabetes (T2D) through activation of the NLRP3 inflammasome." (PMID 35056315, 2021). "The aim of this work is to present a review of the links between the NLRP3 inflammasome, endothelial dysfunction, and type 2 diabetes." (PMID 33546399, 2021). "Glyburide, a sulfonylurea agent for use in Type 2 diabetes, a weak NLRP3 active insulin secretagogue, and its forerunner sulfonamide, 16673-34-0, were added to the INF39 acrylate warhead." (PMID 34443594, 2021). "Reduction of NLRP3 expression in adipose tissue was correlated with improvement of insulin sensitivity in type 2 diabetes patients." (PMID 34832960, 2021). "This review summarizes the links between the NLRP3 inflammasome, endothelial dysfunction, and type 2 diabetes." (PMID 33546399, 2021). "Our results are supported by other reports, where NLRP3 is activated by hyperglycemic conditions and involved in type 2 diabetes." (PMID 34767557, 2021). "Alpha‐lipoic acid alleviates hepatic triglyceride accumulation by suppressing the NLRP3 inflammasome pathway, suppressing lipid generation, and promoting lipid oxidation in high‐fat diet and streptozotocin‐induced type 2 diabetic rats." (PMID 34026086, 2021). "Recently, Chang et al46 identified that NLRP3 inflammasome‐induced pyroptosis contributes to islet inflammation in type 2 diabetes mellitus patients and rats." (PMID 34590363, 2021).
type 2 diabetes (continued). "In those afflicted with type 2 diabetes, enhanced NLRP3 inflammasome stimulation and processing of IL-1β were notably repressed by treatment with the antidiabetic drug metformin via AMPK stimulation." (PMID 34443594, 2021). "The expression levels of NLRP3 inflammasome components are correlated with the disease severity of type 2 diabetes." (PMID 33535473, 2021). "The activation of inflammation complexes such as the NLRP3 inflammasome complex contributes to the development of visceral adiposity, endothelial dysfunction and insulin resistance, precursors to type 2 diabetes (T2D)." (PMID 34940446, 2021). "Neutrophils from diabetic patients for instance showed a four-fold increase in PAD4 levels leading to augmented NETosis, and NLRP3 inflammasome is long well-known in type 2 diabetes." (PMID 34122445, 2021). "TXNIP activates the NLRP3 inflammasome and subsequent secretion of IL-1β in the pathogenesis of type 2 diabetes." (PMID 32842536, 2020). "Our study also takes into account the effect of Myr on NLRP3 inflammasome and oxidative stress markers that aggravate type 2 diabetes." (PMID 32282828, 2020). "The strategy is effective in combatting multiple inflammatory diseases, as evidenced by the mitigation of HFD-induced type 2 diabetes and LPS-induced septic shock in NLRP3 knockout mice." (PMID 32545355, 2020). "It is proved that NLRP3 inflammasome mediated several inflammatory diseases including type 2 diabetes, inflammatory bowel disease and neurodegenerative diseases." (PMID 32754591, 2020). "NLRP3 pathway inhibitors are currently under investigation for a range of inflammatory conditions, including type II diabetes and atherosclerosis, through both indirect and direct pharmacological targeting." (PMID 33042016, 2020). "In type 2 diabetes, chronic hyperglycemia activates NLRP3 inflammasome by promoting the generation of ROS; then, IL-1β induces the dysfunction and destruction of pancreatic islet β cells." (PMID 33584639, 2020). "Second, saturated free fatty acids, such as palmitate, were identified as NLRP3 activators in addition to TLR4 agonists, which eventually cause type 2 diabetes." (PMID 30717382, 2019). "Of note, a recent report documented that bile acids through the TGR5-cAMP-protein kinase A axis inhibit NLRP3 activation and prevent LPS-induced systemic inflammation, alum-mediated peritoneal inflammation, and type 2 diabetes in mouse models." (PMID 31590215, 2019). "Spironolactone treatment reduced the number of active caspase-1-positive-macrophages in the db/db mice, supporting the theory that aldosterone activates the NLRP3 inflammasome in the immune cells of mice with type 2 diabetes." (PMID 31817997, 2019). "Dysfunction in NLRP3 inflammasome activity is known to correlate with several diseases, such as Alzheimer’s disease, type II diabetes mellitus, atherosclerosis, and cancer." (PMID 31416289, 2019). "Third, hyperglycemia activates the thioredoxin-interacting protein (TXNIP)-mediated NLRP3 inflammasome in adipose tissues and microvascular endothelial cells, which are relevant to type 2 diabetes and myocardial ischemic/reperfusion injury, respectively." (PMID 30717382, 2019). "NLRP3 is an inflammasome protein that once activated leads to the processing of IL1β, a cytokine involved in the pathology of type 2 diabetes." (PMID 31164864, 2019). "NLRP3 KO mice demonstrated repression of diabetic nephropathy in type 1 and type 2 diabetes by blocking NLRP3-mediated mitochondrial ROS generation." (PMID 31694192, 2019). "In untreated type 2 diabetic patients, monocytes exhibited increased levels of NLRP3, ASC and pro-inflammatory cytokines." (PMID 29515457, 2018). "Further, PKA activation improved insulin sensitivity in high-fat diet-induced type-2 diabetes through suppression of NLRP3 inflammasome activation." (PMID 29868015, 2018).
type 2 diabetes (continued). "The axis of TXNIP and NLRP3 inflammasome has been confirmed to be an important player in CNS dysfunction or several diseases, such as hippocampus injury, type 2 diabetes, and brain ischemic stroke." (PMID 29386025, 2018). "NLRP3 inflammasome has proved to be involved in the development of many diseases, like stroke, type 2 diabetes, Alzheimer's disease, etc.." (PMID 29853850, 2018). "The role of the NLRP3 inflammasome in autoinflammatory diseases, such as type 2 diabetes (T2D), and autoimmune diseases, such as experimental autoimmune encephalomyelitis (EAE), has been recognized." (PMID 28289409, 2017). "In a series of experiments using in vitro models, intrarenal inflammasome activation elevated intrarenal IL-1β and NLRP3 mRNA levels were increased in both db/db mice (modelling type 2 diabetes) and murine streptozotocin-induced type 1 diabetic mice." (PMID 28708885, 2017). "Glyburide, a drug commonly used in type 2 diabetes, can also prevent NLRP3-dependent IL-1β production." (PMID 28192528, 2017). "There is also evidence in a rat model of type 2 diabetes that Nlrp3 gene silencing ameliorates cardiac inflammation, fibrosis, and function and that NLRP3 inflammasome activation is mediated by increased oxidative stress-induced NF-kB activation." (PMID 27583382, 2016). "Strong correlations between the expression of Nlrp3 inflammasome-related genes and insulin resistance have been recently reported in obese male subjects with impaired glucose tolerance and in type 2 diabetic patients." (PMID 26788246, 2016). "The cardioprotective effects with NLRP3 silencing suggest a potential role for NLRP3 antagonists in treating DCM in type 2 diabetes." (PMID 25136835, 2014). "Glyburide, a type 2 diabetes drug, has been shown to specifically inhibit the NLRP3 inflammasome in response to microbial and crystalline stimuli." (PMID 25254654, 2014). "A number of recent landmark studies have pointed out a key role for an excessive NLRP3 inflammasome activation in the IL-1β-related development of type 2 diabetes." (PMID 23843683, 2013). "Activation of the NLRP3 inflammasome by islet amyloid polypeptide has been also reported in type 2 diabetes." (PMID 22531291, 2012). "The role of NLRP3 inflammasome in a variety of metabolic diseases (including obesity, atherosclerosis and type 2 diabetes) is currently under investigation." (PMID 23060876, 2012). "Studies suggest that the activation of the NLRP3 cascade, leading to the death of macrophages by pyroptosis, might significantly contribute to the delayed wound healing seen in type 2 diabetes (T2D)." (PMID 40170079, 2025). "Although NLRP3 is a well-known instigator of type 2 diabetes, the possibility that the IL-9 pathway could exert its protective effects by regulating the NLRP3 inflammasome has not been investigated thus far." (PMID 40962954, 2025). "Analysis of macrophages from people with type 2 diabetes treated with empagliflozin or sulfonylurea demonstrated that the SGLT2 inhibitor was more efficient in the attenuation of NLRP3 activation in macrophages as compared to sulfonylurea, and more efficiently suppressed IL-1β secretion." (PMID 40004134, 2025). "Finally, we address the safety of NLRP3 inhibition and IL-1 antagonists and the prospect of using this therapeutic approach for the treatment of type 2 diabetes and its comorbidities." (PMID 39496966, 2025). "However, excessive inflammation from abnormal NLRP3 inflammasome activation is closely associated with the development of inflammatory diseases such as atherosclerosis (AS), type 2 diabetes mellitus (T2DM), inflammatory bowel disease (IBD), and neurodegenerative diseases." (PMID 39834360, 2024). "This is followed by “NLRP3 inflammasome: an overview of mechanisms of activation and regulation” with 82 citations, and “Upregulated NLRP3 inflammasome activation in patients with type 2 diabetes” with 76 citations." (PMID 39717099, 2024).
type 2 diabetes (continued). "In addition, previous research reported that Tan I reduced insulin resistance in type 2 diabetes rats as well as osteoarthritis in mice, NLRP3 inflammasome activation also act as a key role in the progression of type 2 diabetes as well as osteoarthritis." (PMID 37400760, 2023). "The monoclonal antibody of IL-1β, canakinumab, could suppress NLRP3 inflammasome signaling and significantly reduce systemic inflammation in type 2 diabetes patients infected with SARS-CoV-2." (PMID 37515138, 2023). "Therefore, excessive activation of the NLRP3 inflammasome can promote the development of various inflammatory diseases, such as sepsis, arthritis, atherosclerosis, type 2 diabetes, AD, and cancer." (PMID 37915104, 2023). "Likewise, another biaryl compound, glyburide, with an intrachain and a sulfone group, also inhibits NLRP3 in spite of its main therapeutic indications toward type 2 diabetes." (PMID 35566202, 2022). "In addition, D-ribose promotes NLRP3 inflammasome activation in type 2 diabetes to induce podocyte injury and glomerulosclerosis, the caspase-1 inhibitor YvAD significantly blocks podocyte injury." (PMID 36387904, 2022). "Previous studies revealed the activation of nucleotide-binding and oligomerization domain-like receptor family pyrin domain-containing 3 (NLRP3) inflammasome in DM patients via a ROS-mediated pathway, which would impair wound healing in mice and humans with type 2 diabetes." (PMID 33738117, 2021). "In addition, monocytes derived from newly identified patients with untreated type 2 diabetes displayed increased NLRP3 inflammasome activation compared with healthy subjects." (PMID 34576117, 2021). "However, recent studies have shown that the NLRP3 inflammasome is also involved in the molecular etiology of numerous chronic inflammatory diseases, including type 2 diabetes, non-alcoholic steatohepatitis, and heart failure." (PMID 34943988, 2021). "Concluded that as insulin resistance and chronic inflammation are predisposing factors to type 2 diabetes mellitus (T2DM), through “NOD-like receptor pyrin domain containing-3” (NLRP3) inflammasome component of innate immunity, a metabolic stress sensor, modulated by dietary and genetics factors." (PMID 32650619, 2020). "Moreover, the anti-type 2 diabetes drug glyburide, has been shown to inhibit NLRP3 inflammasome activation and consequent microbial ligand-, DAMP-, and crystal-induced IL-1β secretion." (PMID 32550001, 2020). "Macrophage-specific knockdown and/or peripheral blocking of CB1R via the non-CNS-penetrant CB1R inverse agonist JD5037 improved the pathology of type-2 diabetes and re-established normoglycemia by reducing the expression of cardinal NLRP3 inflammasome proteins." (PMID 33584697, 2020). "Despite increasing evidence of the relationship between the NLRP3 inflammasome, mitochondrial dysfunction and oxidative stress, and of their participation in type 2 diabetes physiopathology, therapeutic strategies to combat type 2 diabete, which target NLRP3 inflammasome, are yet to be consolidated." (PMID 32545788, 2020). "Therapeutic potentials of several NLRP3 targeting miRNAs were investigated in autoimmune diseases such as inflammatory bowel diseases (IBDs), RA, type 1 diabetes (T1D), type 2 diabetes (T2D), and systemic lupus erythematosus (SLE)." (PMID 31118894, 2019). "As another important member of inflammasomes, NLRP3 inflammasome, which is receiving more attention and has been better characterized in recent years, is involved in a number of diseases, including type II diabetes mellitus, renal disease and neurodegenerative disorders." (PMID 31416289, 2019). "We tested the hypothesis that vascular dysfunction in type 2 diabetes is mediated by the activation of MR and assembly of the NLRP3 inflammasome." (PMID 31817997, 2019). "Interestingly, in the context of type 2 diabetes, the NLRP3 inflammasome is a sensor of metabolic stress." (PMID 30424795, 2018).
type 2 diabetes (continued). "NLRP3 inflammasome is involved in metabolic disorders, such as type 2 diabetes and obesity." (PMID 29941940, 2018). "Similarly, amyloid-β fibrils and islet amyloid polypeptide (IAPP) activate NLRP3, which contributes to Alzheimer’s disease and the progression of type 2 diabetes, respectively." (PMID 24367371, 2013). "Here, we outline the new immunological mechanisms that link metabolic dysfunction to the emergence of chronic inflammation and discuss the opportunities and challenges of future therapeutic approaches to dampen NLRP3 inflammasome activation or IL-1β signaling for controlling type 2 diabetes." (PMID 23483669, 2013). "Masters and colleagues demonstrated that soluble oligomers of islet amyloid polypeptide (IAPP), a protein that forms amyloid deposits in the pancreas during type 2 diabetes, could be endocytosed and trigger the NLRP3 inflammasome and generate mature IL-1β." (PMID 23762269, 2013). "Additionally, type 2 diabetic patients showed elevated levels of NLRP3, ASC, IL-1β, and IL-18 mRNA and protein expression in monocyte-derived macrophages, compared with those in healthy control subjects." (PMID 23843683, 2013). "There are some observations that amyloid fibrils, e.g. islet amyloid polypeptides (IAPP) and Alzheimer×s amyloid-β, can trigger NLRP3 inflammasomes and in that way stimulate inflammation and enhance pathogenesis in type 2 diabetes and Alzheimer×s disease, respectively." (PMID 22411934, 2012). "Moreover, inhibition or silencing NLRP3 gene ameliorates DCM in type 2 diabetes rat." (PMID 38987672, 2024). "Interestingly, myofibers cultured in high glucose presented elevated NLRP3 levels, strongly suggesting the activation of the inflammasome as occurs in type 2 diabetes patients, which generates pro-inflammatory cytokines that have been shown to induce Cx expression." (PMID 37189454, 2023). "In a mouse model of type 2 diabetes mellitus (T2DM), QA extract effectively attenuates renal fibrosis in a NLRP3 inflammasome-dependent manner." (PMID 33390969, 2020). "The NLRP3 inflammasome is closely related to various heritable and acquired diseases, especially inflammation-driven diseases, such as gout, cardiovascular diseases, type 2 diabetes, Alzheimer’s disease, prion diseases, infectious diseases, gynecological diseases, and obstetrical complications." (PMID 33584639, 2020). "Reports also revealed that excessive activation of NLRP3 inflammasome could play an important role in other diseases, such as multiple sclerosis, Alzheimer’s disease, metabolic disorders, such as gout, atherosclerosis and type 2 diabetes." (PMID 29868015, 2018). "In addition, NLRP3 inflammasome activation and production of IL-1β are upregulated in the peripheral mononuclear cells of drug-naïve type-2 diabetic patients, suggesting a role of the inflammasome in the pathogenesis of type-2 diabetes." (PMID 30404221, 2018). "Overall these data reveal a novel metabolic function of the NLRP3 inflammasome in adipose tissue, suggesting that its pharmacological modulation in obese and/or patients with type 2 diabetes may restore the metabolic function of adipose tissue and subsequently improve insulin sensitivity." (PMID 23843683, 2013). "In patients with type 2 diabetes, SGLT2 inhibitors decrease the levels of proinflammatory cytokines (TNF-α, IL-6, and IL-1β) and attenuate the activity of NLRP3 inflammasome." (PMID 40004134, 2025). "Thus, NLRP3 inflammasome expression levels correspond with Type 2 diabetes mellitus (T2DM) severity." (PMID 38659578, 2024). "In contrast, studies have shown that low-dose glibenclamide (a type 2 diabetes drug that inhibits K-ATP channels in pancreatic β cells) downregulates TGF-β1, NLRP3, ASC, TGF-β1, NLRP3, and ASC expression induced by thioacetamide." (PMID 36378463, 2023). "The abnormal activation of NLRP3 inflammasome is closely related to the occurrence and development of a variety of abnormalities, such as CAPS, type 2 diabetes, AD, and so on." (PMID 37125240, 2023).